ENSG00000303695 (novel transcript, sense overlapping PPIAL4F)
Gene: Long non-coding RNA gene on chromosome 1 (144,552,284 to 144,601,547, forward strand). Ensembl gene ENSG00000303695.
Gene Ontology:
Molecular function: triplet codon-amino acid adaptor activity
Biological process: translation